LINC03057 (long independently transcribed non-coding RNA 3057)
Synonyms: lnc-HOXB8-1:2; RP11-357H14.17
Gene: Long non-coding RNA gene on chromosome 17 (48,634,804 to 48,647,050, reverse strand). Ensembl gene ENSG00000272763.
Diseases named in the same sentence as LINC03057 in open-access papers:
LINC03057 is named in the same sentence as 4 diseases in open-access papers, as found by Europe PMC text mining. Sharing a sentence is not in itself a finding about the gene and the disease. The quoted sentences say what the papers report.
colorectal cancer (1 paper, 2025). A primary or metastatic malignant neoplasm that affects the colon or rectum. "LINC03057 acts as an miRNA sponge by negatively regulating hsa-miR-6825-5p, inducing tumor-associated macrophage infiltration, which promotes the progression of neuroendocrine differentiated colorectal cancer." (PMID 40863726, 2025). "LINC03057, also known as lnc-HOXB8-1:2 (ENSG00000272763), is an oncogenic lncRNA associated with colorectal cancer progression." (PMID 40863726, 2025).
endometrial carcinoma (1 paper, 2025). A malignant tumor arising from the epithelium that lines the cavity of the uterine body. "LINC03057 (also known as lnc-HOXB8-1:2 or RP11–357H14.17) is a lncRNA associated with the progression of different tumors, such as colorectal, gastric and endometrial carcinoma, with shortened overall survival and poor prognosis." (PMID 40863726, 2025).
LINC03057 also shares sentences with these, for which no sentence is quoted: cancer (1 paper); tumor (1).